UGT2B7 (UDP glucuronosyltransferase family 2 member B7)
Diseases named in the same sentence as UGT2B7 in open-access papers (continued):
Sharing a sentence is not in itself a finding about the gene and the disease.
cancer (15 papers, 2011 to 2024). A tumor composed of atypical neoplastic, often pleomorphic cells that invade other tissues. "Many previous studies evaluated the role of UGT2B7 rs7439366 SNP on cancer risk." (PMID 33595913, 2021). "Thus, factors affecting the expression and enzyme activity of UGT2B7 may play an important role in tumorigenesis, of which the UGT2B7 mutation may be one of the essential factors involved in the occurrence and development of cancer." (PMID 33595913, 2021). "The relationship between SNPs in UGT2B7 and the efficacy of morphine treatment in cancer pain was investigated in 120 Chinese cancer patients." (PMID 36422103, 2022). "UGTs genes are upregulated in tissues associated with drug metabolism, such as cancers of the liver, kidney, intestine, and pancreas, such as UGT1A6, UGT1A9, UGT1A10, UGT2A3, UGT2B7, and UGT8, and they are significantly associated with increased overall survival in cancer." (PMID 36741721, 2022). "Similarly, the extensive glucuronidation of epirubicin in the liver by UGT2B7 leads to drug excretion into the bile and urine and is a component of cancer cell resistance." (PMID 33915981, 2021). "Thus, drug-induced UGT2B7 activity in cancer cells affected the therapeutic efficacy of cytotoxic drugs and noncytotoxic drugs, which were UGT2B7 substrates." (PMID 32382038, 2020). "Five core ADME genes coding for phase II drug metabolism enzymes showed significant associations of their intratumoral expression levels with OS rates in cancers, including GSTP1, NAT1, UGT1A1, UGT2B15, UGT2B7." (PMID 33202946, 2020). "The CYP2D6*10 SNP is relevant to tramadol pharmacokinetics and opioid dose requirement, while SNPs within UGT2B7 (rs7439366), ABAT (rs1641025), and P2RX7 (rs1718125) have demonstrated some level of potential clinical relevance to cancer pain pharmacogenomics in Asian patients." (PMID 36422103, 2022). "The UGT2B7 gene encodes UDP-glucuronosyltransferase-2B7, involved in phase II metabolism, conjugating a variety of compounds such as analgesics (morphine), carboxylic non-steroidal anti-inflammatory drugs (ketoprofen) and anti-cancer drugs (all-trans retinoic acid)." (PMID 36292717, 2022).
tumor (8 papers, 2012 to 2025). "UGT2B7 was upregulated in female NSCLC patients’ tumor tissues and was associated with a poor prognosis in NSCLC." (PMID 33595913, 2021). "In the batch normalized combined data set of GSE32863 and GSE37764, compared to adjacent normal tissues, UGT2B7 was high expressed in tumor tissues (p = 0.012)." (PMID 33595913, 2021). "UGT2B7 is one of the main metabolism enzymes to catalyze many endogenous compounds such as retinoic acid, estriol and exogenous drugs including anti-tumor zidovudine (AZT) and epirubicin." (PMID 28418861, 2017). "Results indicated that the protein expression of UGT2B7 was much higher in normal colorectal cells than tumor ones." (PMID 28418861, 2017). "Consistent with the data analyzed by SYBR-Green quantitative polymerase chain reaction (qPCR), UGT2B7 mRNA expression was significantly declined in tumor tissues compared to adjacent normal tissues." (PMID 28418861, 2017). "The pairwise correlation of UGT1Asand UGT2B7 amongmetabolic activities, protein expression ratio and mRNA expression ratio in the adjacent normal tissues or tumor tissues." (PMID 26010150, 2015). "Comparing with other correlations, the metabolic activity ratio of UGT1As and UGT2B7, which means the reduction ratio of metabolic activity in tumor tissues, was closely related to the protein reduction ratio of these enzymes." (PMID 26010150, 2015). "Subsequently, the relative protein and mRNA expression levels of UGT2B7 were significantly decreased in tumor tissues." (PMID 26010150, 2015). "And in turn, the significantly impaired function of UGT1As and UGT2B7 in tumor tissues implied their down-regulated translational activities, which were reported as the predisposing factors for hepatocarcinogenesis." (PMID 26010150, 2015). "In our following study, notable reductions in the protein and gene expression levels of UGT1As and UGT2B7 were subsequently observed in most of tumor tissues compared to that in adjacent normal tissues." (PMID 26010150, 2015). "By utilizing certain specific substrates for UGTs, we initially demonstrated that catalytic activities of UGT1A, UGT1A1, UGT1A4, UGT1A9 and UGT2B7 were significantly decreased in the tumor tissues in HBV-positive HCC patients." (PMID 26010150, 2015). "Specially, the precise information on the alteration of UGT1As and UGT2B7 in HBV-positive HCC tumor and the adjacent normal liver tissues is currently unavailable." (PMID 26010150, 2015). "In addition, PGR, as well as UGT2B15 and UGT2B7, which were the non-tumor-related genes identified among the 29 targeted genes, were found to be related to overall survival in CRC patients." (PMID 36843944, 2023). "Our findings imply that enzymatic activity enhancement and substrate regioselective catalysis alteration of UGT2B7 may release morphine tolerance under the cure of tumor-induced pain." (PMID 28418861, 2017). "This phenomenon may give us an explanation why younger CRC patients held higher expression level of UGT2B7 in their normal colorectal tissues compared to the tumor ones." (PMID 28418861, 2017). "The purpose of this study was to determine whether this mechanism can finally transform the enzymatic activity of UGT2B7 then affect morphine regioselective glucuronidation, our conclusion may guide for morphine application in tumor-induced pain." (PMID 28418861, 2017). "Given the increasing incidence and mortality of HCC with the high HBV-infection background in China, we systematically analyzed the metabolic function, protein and gene expression levels of UGT1A, UGT1A1, UGT1A9, UGT1A4 and UGT2B7 in HBV-positive HCC tumor and the adjacent normal tissues." (PMID 26010150, 2015). "Furthermore, the differential expression of the top five genes (C6, UGT2B7, SLC22A1, F11, and CYP2C8) in the RF model between normal and tumor tissues was validated using the GSE25097 and TCGA datasets." (PMID 39548390, 2024).
tumor (continued). "Furthermore, we validated the differential expression of the top five genes (C6, UGT2B7, SLC22A1, F11, and CYP2C8) between normal and tumor tissues using the GSE25097 and TCGA datasets." (PMID 39548390, 2024). "UGT2B15 and UGT2B7, which are non-CRC tumor-associated genes that were identified in the normal expression group, were found to be correlated with overall survival in CRC patients." (PMID 36843944, 2023). "Meanwhile, results from the transcriptome sequencing analysis from never‐smoking Chinese female NSCLC patients shown that UGT2B7 mRNA was upregulated in tumor tissues (data were not shown), 4098 genes were identified." (PMID 33595913, 2021). "The results revealed that in the tumor human liver microsomes (HLMs), either Vmax (maximum reaction rate, Rmax for UGT1A1) or the clearance rates (Vmax/Km, Clint) of UGT1A, UGT1A1, UGT1A4, UGT1A9 and UGT2B7 were significant lower than those of in the adjacent normal HLMs." (PMID 26010150, 2015).
benign tumors (1 paper, 2015). "And complementary to the fact that the gene and protein expression levels of UGTs were not altered in the benign tumors, we also found that the metabolic activities of UGT1As and UGT2B7 in the adjacent normal HLMs were consistent with that of in the commercial (absolute normal) HLMs." (PMID 26010150, 2015).
infection (1 paper, 2025). The state of being infected such as from the introduction of a foreign agent such as serum, vaccine, antigenic substance or organism. "Another genetic variant, UGT2B7 c.802C>T (rs7439366), was identified with contributions to increased susceptibility to infections, particularly Pneumocystis carinii pneumonia." (PMID 40630120, 2025).
metabolic disease (1 paper, 2023). A congenital disorder (due to inherited enzyme abnormality) or acquired (due to failure of a metabolically important organ) disorder resulting from an abnormal metabolic process. "UDP-Glucuronosyltransferase Family 2 Member B7 (UGT2B7) is the most common UGT2B member, located on the mitochondrial membranes, endoplasmic reticulum membranes, and the nuclear membranes of human cells, and it was widely studied because of the high correlation with metabolic diseases." (PMID 38068799, 2023).
UGT2B7 also shares sentences with these, for which no sentence is quoted: autoimmune hepatitis (1 paper); benign prostatic hyperplasia (1); bilirubin metabolic disorder (1); coronary heart disease (1); diarrheal disease (1); esophageal squamous cell carcinoma (1); Gilbert syndrome (1); headache disorder (1); hepatitis C (1); hypertensive disorder (1); ischemic stroke (1); kidney disease (1); leukopenia (1); liver diseases (1); lung carcinoma (1); metastatic melanoma (1); non-alcoholic fatty liver disease (1); ovarian carcinoma (1); panic attacks (1); primary biliary cholangitis (1); primary sclerosing cholangitis (1); respiratory infection (1); thyroid carcinoma (1); vivax malaria (1).